GOLGA8T (golgin A8 family member T)
Tractability: No criterion of Open Targets' tractability assessment is met for any kind of drug.
Gene: Protein-coding gene on chromosome 15 (30,135,051 to 30,148,748, forward strand). Ensembl gene ENSG00000261247.
Gene Ontology:
Biological process: Golgi organization
Cellular component: cis-Golgi network; Golgi cis cisterna; Golgi cisterna membrane; Golgi apparatus
Genetic constraint (gnomAD): Loss-of-function variants: 11 observed, 19.23 expected, observed/expected ratio (o/e) 0.57, 90% interval 0.36 to 0.95. The upper end of that interval is the gene's LOEUF score, 0.95, which puts it in group 4 of 6, group 1 being the genes least tolerant of losing a copy. Missense variants: 81 observed, 162.59 expected, observed/expected ratio (o/e) 0.5, 90% interval 0.41 to 0.6. Synonymous variants: 44 observed, 56.03 expected, observed/expected ratio (o/e) 0.79, 90% interval 0.62 to 1.01.
Homologues: Orthologues: mouse Golga2 (45% identical), dog GOLGA2 (44% identical), tropical clawed frog golga2 (34% identical), zebrafish golga2 (29% identical), Drosophila melanogaster GM130 (23% identical), Caenorhabditis elegans golg-2 (19% identical), rat Golga2l1 (5% identical). Paralogues in human: GOLGA8K (99% identical), GOLGA8J (98% identical), GOLGA8H (97% identical), GOLGA8M (96% identical), GOLGA8N (90% identical), GOLGA8O (90% identical), GOLGA8Q (90% identical), GOLGA8R (89% identical), GOLGA8S (84% identical), GOLGA8F (81% identical), GOLGA8G (81% identical), GOLGA8A (66% identical), and 6 more.